JAK2 (Janus kinase 2)
Diseases named in the same sentence as JAK2 in open-access papers (continued):
Sharing a sentence is not in itself a finding about the gene and the disease.
cancer (continued). "The Janus kinase 2 (JAK2) amplification was documented to be simultaneously activated with 9p24.1 chromosome copy number amplification and upregulated PD-L1 expression in primary cancers, suggesting a possible transactivation between JAK2 and PD-L1 genes." (PMID 29910728, 2018). "Therefore, our results establish a mechanistic link between the inhibition of JAK2/STAT3 signaling and the anti-cancer therapy of targeting miR-196b-5p in CRC cells." (PMID 28591704, 2017). "Thus, our results suggested that low expression of miR-375 activates JAK2/STAT3 and MAP3K8/ERK pathways in cancer cells, which in turn promotes cell proliferation." (PMID 28186962, 2017). "First, as previously reported, deletions of chromosome 9p were not contiguous, suggesting that deletion of JAK2 conferred a functional selection advantage to the cancer cells." (PMID 28977839, 2017). "Crytotanshinone (CPT) showed potential therapeutic value in animal breast model through enhancing cytotoxic CD4+ T cells by up-regulating JAK2 and STAT4 phosphorylation, suggesting that STAT4 may be play opposite function with STAT3 in human cancers." (PMID 28422733, 2017). "However, many ERα + cancers that develop in this model are very aggressive, and display highly activated ERK1/2 and AKT, indicating activation of non-JAK2/STAT5 pathways." (PMID 28103936, 2017). "These include cancer hallmarks of various types: oncogenes (BCL2, BRAF), caspases (CASP6/7), transcription factors (E2F3), cell cycle genes (CDC42, CDK2, CDKN2A), cancer related kinases (JAK2/3, MAPK4/6/14) and DNA repair genes (BRCA1, PARP1 and RAD50)." (PMID 28059167, 2017). "OPN secreted by TM4SF4/GSK3β/β-catenin signaling activated the JAK2/STAT3 or FAK/STAT3 pathway, which also up-regulates OPN expression in an autocrine manner and consequently maintains the self-renewal and metastatic capacity of cancer cells." (PMID 29254164, 2017). "Furthermore, icaritin suppressed the expression of p-JAK2 and p-STAT3 in mice carcinoma tissue, which was consistent with our results in vitro." (PMID 28085115, 2017). "Importantly, treatment with peptide 520 suppressed JAK2, phospho-STAT3 protein expression, and induced cancer cell death in a dose-dependent manner." (PMID 27409672, 2016). "To investigate whether MEK inhibitors activate JAK2/STAT3 signal pathways, we examined the effects of MEK inhibitors in K-Ras mutant cancer cell lines." (PMID 25961376, 2015). "Nonetheless, interaction of SOCS1 with Elongins is dispensable for SOCS-dependent inhibition of JAK2 and overexpressed Elongins/SOCS1 do not destabilize wild-type JAK2 in cancer cells." (PMID 24833526, 2014). "Given that there are no known naturally occurring activating mutations in the STAT3 gene, aberrant activation of STAT3 in many types of cancers is primarily due to overexpression or deregulation of upstream signaling molecules such as IL-6/gp130, EGF/EGFR, JAK2, or Src." (PMID 24260381, 2013). "Also, our current observation indicates that the c-Myc-ODC axis has an essential role in JAK2 (V617F)-induced tumorigenesis, and suggests that DFMO would also be useful as an anti-cancer drug for MPNs." (PMID 23300995, 2013). "Cuc IIa is a novel class of anti-cancer drug in suppression of cancer cell expansion by disrupting the actin cytoskeleton and directing the cell to undergo PARP-mediated apoptosis through the inhibition of survivin downstream of JAK2/STAT3." (PMID 21304528, 2011). "Collectively, our data suggest that TYK2, JAK1 and JAK2 are novel targets that may prove useful to circumvent drug resistance mediated by FGF-2, a growth factor often secreted by cancer cells, or their supporting tissues, and elevated in cancer patients." (PMID 21625473, 2011). "As survivin is a potential downstream target of JAK2/STAT3 pathway, we further explored whether Cuc IIa also inhibited cancer cell expansion by inhibiting JAK2/STAT3 activation." (PMID 21304528, 2011).
cancer (continued). "We found that the NF-κB pathway was the most important, but not an essential, regulator of IL-6 secretion in the tested cancer samples and that Jak2/Stat3 pathway contributed substantially to the regulation of IL-6 secretion in many cancer samples." (PMID 21122157, 2010). "Consistent with previous literature, we found that drug resistant cancer cells secreted more IL-6 secretion than the parental cells, and not only NF-κB, PI3-K/Akt and MEK/Erk but also Jak2/Stat3 pathway contributed to the autocrine production of IL-6 in these cells." (PMID 21122157, 2010). "Furthermore, FLLL32 was found to be potent than other reported JAK2/STAT3 inhibitors, including FLLL32, WP1066, AG490, Stattic, S3I-201, and curcumin in our cancer cell lines." (PMID 20712901, 2010). "Therefore, Jak2/Stat3, MEK/Erk and PI3-K/Akt pathways individually contribute to the regulation of IL-6 autocrine production in cancer cells." (PMID 21122157, 2010). "The potential interaction between JAK2-mediated signaling pathways and cell cycle control functions modulated by CHEK2 could shed light on shared mechanisms or synergies in the pathogenesis of certain hematologic disorders and malignant neoplasms." (PMID 40177144, 2025). "To investigate the role of IFNγ in PD-L1 upregulation, we first incubated cancer cells without or with CD64-CR T cells in the presence or absence of a scalar dose of the JAK2 inhibitor ruxolitinib, which inhibited the upregulation of PD-L1 in a dose-response manner." (PMID 39962623, 2025). "However, we identified that treatment of primary hepatocytes with C15:0 and C17:0 suppresses JAK2/STAT3 signaling, which may indicate an anti-cancer and anti-NAFLD effect of OCFA." (PMID 37432205, 2023). "Additionally, the protein expression results showed that corosolic acid could hinder the activation of both JAK2 and STAT3 proteins within these cancer cells by inhibiting the phosphorylation and activation of these proteins." (PMID 37009004, 2023). "Finally, four fundamental cancer genotypes are defined: the wild-type (no mutation), the TET2 single mutant, the JAK2 single mutant and the double mutant (in either order)." (PMID 36192425, 2022). "However, no mutations were identified in the cancer hotspot locations of IL23R, IL12Rß1, IL12Rß2, OSMR, TYK2, and JAK2 across all mutant distributions." (PMID 36232773, 2022). "Moreover, QC-mediated anti-inflammatory and anti-apoptotic properties play a key role in cancer prevention by modulating the TLR-2 (toll-like receptor-2) and JAK-2/STAT-3 pathways and significantly inhibit STAT-3 tyrosine phosphorylation within inflammatory cells." (PMID 36233051, 2022). "Cervical cancer-secreted exosomal miR-1468-5p epigenetically activates the JAK2/STAT3 pathway in lymphatic endothelial cells by directly targeting homeobox containing 1 (HMBOX1) in the SOCS1 promoter, activating an immunosuppressive program that allows cancer cells to escape anti-cancer immunity." (PMID 36358833, 2022). "Janus kinase 2 (JAK2) is a tyrosine kinase that activates the signal transducer and activator of transcription 3 (STAT3) transcription factor, which has been involved in the progression of most types of cancers including GB, which is required for GSC growth and self-renewal." (PMID 35562901, 2022). "ANXA1 also promotes the proliferation and metastasis of cancer cells through the binding of EphA2, the suppression of autophagy and the activation of the PI3K/AKT pathway and promotes proliferation and migration via the regulation of the IL-6/JAK2/STAT3 pathway." (PMID 34439260, 2021).
cancer (continued). "Interestingly, chloroquine, an autophagy inhibitor, was found to significantly lower the proportion of cancer stem cells in triple negative BC, by concurrently reducing the expression of JAK2 and DNMT136." (PMID 32895373, 2020). "Moreover, in obese patients, the cytokines produced by adipocytes and immune cells could promote the survival of cancer stem cells (CSCs) through the activation of the Notch3 and IL-6/JAK2/STAT3 pathways, as demonstrated in other cancer models." (PMID 30366466, 2018). "Second, there were cases in TCGA tumors and CCLC cancer cell lines in which JAK2 was deleted in the absence of CDKN2A/CDKN2B or PTPRD deletion, suggesting that JAK2 deletion alone may have a functional benefit to cancer cells." (PMID 28977839, 2017). "Indeed, EPO antagonized trastuzumab-induced therapeutic effects through JAK2-mediated activation of SRC and inactivation of PTEN protein, so combined therapy of HER2-positive cancer cells with EPO and trastuzumab reduced the response of these cells to trastuzumab both in vitro and in vivo." (PMID 25426117, 2014). "Both the NF-κB/IL6/JAK2/STAT3 cascade, which we show here is modulated by miR-221/222-mediated downregulation of ADIPOR1, and ZEB2 expression, which we have previously shown is repressed by TRPS1, are well-characterized effector pathways in cancer metastasis, invasion, and EMT." (PMID 23776679, 2013). "In addition to Jak2/Stat3 pathway, PI3-K/Akt and MEK/Erk could also contribute to the regulation of IL-6 autocrine production in cancer cells." (PMID 21122157, 2010). "Since early STAT3 activation was regulated by fibronectin-JAK2, and its long-term activation was maintained by the cytoplasmic LMO2-LDB1 complex, phosphorylation of STAT3 on the cells cultured on polymer X might play an important role in regulating cancer stem-like properties in these cells." (PMID 36359204, 2022). "However, the JNK or JAK2 inhibitor could neither augment the anti-cancer effects of pKAL on STAT3 activity, nor on the expressions of CD44, Oct 3/4, β-catenin, and MMP-9 of RT-R-MDA-MB-231 cells." (PMID 32326231, 2020). "Consequently, JAK2 and TBK1 inhibitors may have utility in this cancer." (PMID 30105668, 2019). "However, the anti-cancer effects of icariin in MM cells had not been extensively investigated, although icaritin a hydrolitic product of icariin has been reported to modulate IL-6/JAK2/STAT3 signaling cascade in MM." (PMID 29899697, 2018). "Furthermore, it is not known whether human cancer cells require Aurora A and JAK2 alone or together to survive, to grow in an anchorage-dependent and –independent manner as well as invade and metastasize." (PMID 24930769, 2014). "Some of the transcriptomic alterations corresponded to typically altered genes and processes in cancer and Ph-negative MPN patients that are known to be triggered by mutant calreticulin without the intervention of JAK2/MPL." (PMID 36611979, 2023). "CT induced apoptosis of esophageal EC109 cancer cells by inhibiting p-STAT3 (Tyr705) and p-JAK2 without effect on the expression of the total STAT3 and JAK2 in vitro and in vivo." (PMID 32265690, 2020). "In addition, oncostatin M has been shown to induce EMT in tubular epithelial cells through GP130-mediated activation of JAK2/STAT3 pathway, indicating that this pathway may be critical for cytokine and growth factor-mediated responses regulating EMT biology in fibrogenesis and cancer." (PMID 19088723, 2009). "Also, the same authors reported that DU145 cancer invasion into tissues was dependent on the Src and integrin pathway and not on those involving PI3K, JAK-2, NFkB, and RAC, as the cells that were transfected with COMP invaded more than those mock-transfected." (PMID 38892202, 2024). "Regarding upstream signaling, the JNK or JAK2 inhibitor could inhibit STAT-3 activation in RT-R-MDA-MB-231 cells, but not augmented pKAL-induced anti-cancer effects." (PMID 32326231, 2020).
cancer (continued). "However, the potential anti-cancer effects of garcinol in HCC cancer model and in the context of STAT3/JAK2 signaling cascade as well as STAT3 acetylation have not been investigated yet." (PMID 24655440, 2014).
hematologic malignancies (96 papers, 2009 to 2026). "Given the prevalence of underlying hematological disorders, it is essential to investigate somatic mutations in the JAK2, including V617F and exon 12 mutations, as well as mutations in the CALR and MPL genes." (PMID 40242703, 2025). "The first evidence of JAK gain-of-function mutations in hematological disorders, which preceded discovery of the JAK2-V617F mutation by 10 years, was provided by the Drosophila tumorous-lethal (Tum-l) mutation in the kinase-like domain of the hopscotch locus." (PMID 40140631, 2025). "We conducted a narrative review of landmark discoveries in hematological malignancies and Jak2, focusing on its role in oncogenesis, risk stratification, and drug resistance in MPNs." (PMID 41226376, 2025). "Dysregulation of JAK2, particularly due to mutations such as the V617F mutation, is commonly implicated in the development and progression of hematological malignancies, including pediatric leukemia." (PMID 40486651, 2025). "JAK2 plays a crucial role in immune regulation, inflammation, and hematopoiesis, and its dysregulation is implicated in several hematologic malignancies." (PMID 41300763, 2025). "This mutation causes the JAK2 protein to be constitutively active, which is very common in certain hematological diseases." (PMID 41369330, 2025). "For instance, JAK2 V617F mutation is associated with a variety of hematologic malignancies and can confer resistance to chemotherapy and other tyrosine kinase inhibitors." (PMID 40486651, 2025). "Given its substrate targets (e.g. BAF155 and RUNX1) and gene targets (e.g. BMI-1 and ID2), CARM1 and phospho-CARM1 appear to play a pivotal role in hematologic malignancies with the JAK2-V617F mutation, and likely in other settings as well." (PMID 38649367, 2024). "Other JAK2 somatic mutations found in exon 12, R683 and T875, have also been linked to hematological malignancies." (PMID 35954343, 2022). "Polycythemia vera (PV) is a malignant clonal hematological disease of hematopoietic stem cells characterized by the proliferation of peripheral blood cells, and JAK2 mutation is one of the main causes of PV peripheral blood cell proliferation." (PMID 36230834, 2022). "Bone marrow abnormalities associated with the JAK-2 somatic mutation represent an important subset of hematological disorders, with various systemic manifestations, including CNS." (PMID 35493844, 2022). "The activating JAK2-V617F mutation is a driver of myeloproliferative neoplasia (MPN) a preleukemic blood disorder." (PMID 31398915, 2019). "Our data suggest the prevalence JAK2 mutation in other hematological disorders including CML, AML, and ALL." (PMID 31870101, 2019). "JAK mutations have also emerged in other hematologic diseases, and the majority of the pathogenic mutations in JAK2 (also in JAK1 and JAK3) localize in or near the pseudokinase domain." (PMID 26377485, 2016). "The aim of the present study was to investigate the occurrence of the JAK2 gene mutation in 140 clinical samples, and to evaluate its clinical significance in MPNs and other hematological diseases." (PMID 25624900, 2015). "Hyperactive Jak2 signaling has been implicated in numerous hematological disorders as well as in various solid tumors including GBM." (PMID 25162558, 2014). "HSP90 has been associated with the stabilization of mutant forms of oncogenes including the Jak2 mutation V617F in hematologic diseases." (PMID 19607667, 2009). "In hematologic malignancies, somatic gain-of-function mutations in JAKs—especially JAK2—are common." (PMID 41153712, 2025). "Next, we sought to replicate our primary findings from the UK Biobank and establish whether the presence of co-occurring mCA and JAK2/DNMT3A impact the risk of subsequent development of hematologic malignancies (HM)." (PMID 38225345, 2024).
hematologic malignancies (continued). "Detection of these highly clonal, co-occurring CH events, especially at TET2, DNMT3A, and JAK2, could be helpful in identifying individuals at increased risk of developing hematologic malignancies." (PMID 37684235, 2023). "Most JAK2 mutations associated with hematological malignancies encode missense mutations that localize within JAK2 exon 12 of SH2L-JH2 linker region, or within JAK2 exons 14 or 16 of the pseudokinase domain, highlighting these regions as oncogenic hot-spots for mutation." (PMID 35903543, 2022). "JAK2 mutations have been observed in malignancies and hematologic diseases." (PMID 36497424, 2022). "These conditions, as well as the hematological diseases related to somatic gain-of-function mutations of JAK2 and STAT3 respectively in myeloproliferative diseases (MPNs) and large granular leukemia (LGL), illustrate the key role of this signaling pathway in the regulation of the immune response." (PMID 34603291, 2021). "These fusions lead to a constitutive activation of JAK2-TK, a key driver in the pathogenesis of various hematological malignancies." (PMID 41530508, 2026). "JAK2 inhibitors, such as ruxolitinib, have shown efficacy in adult hematologic malignancies and are being evaluated in pediatric settings." (PMID 40486651, 2025). "For instance, gain-of-function mutations in JAK2 are frequently found in myeloproliferative disorders, while alterations in other JAK family members have been linked to immune imbalance and hematologic malignancies." (PMID 41153712, 2025). "ETV6::JAK2 (TEL::JAK2) is found in various hematologic malignancies and results in constitutive kinase activity." (PMID 40140631, 2025). "JAK2, a member of the JAK family, is primarily associated with treating and preventing hematological disorders." (PMID 40362240, 2025). "Targeted therapies that inhibit JAK-STAT signaling, such as JAK2 inhibitors (e.g., ruxolitinib and fedratinib), have shown efficacy in adult hematologic malignancies and are being explored in pediatric settings." (PMID 40486651, 2025). "Our study included patients with various hematological diseases, including PMF (all of whom had JAK2 V617F mutations), MDS, MM, ET, and PV." (PMID 38496121, 2024). "The ruxolitinib PK and preliminary PD phase I study has been performed in children with oncologic or hematologic malignancies with assessment of JAK2 and STAT5 phosphorylation as readout." (PMID 34603291, 2021). "Gain of function mutations, translocations, and amplifications involving the JAK2 gene and leading to constitutive activation of the JAK2 kinase have been reported in various hematological malignancies." (PMID 31885183, 2020). "JAK-2 dysregulation plays an important role as an oncogenic driver, and is thus a promising therapeutic target in hematological malignancies." (PMID 29262601, 2017). "JAK-2 dysregulation plays an important role as an oncogenic driver, prompting increasing interest in JAK-2 inhibitors for therapy against hematological malignancies." (PMID 29262601, 2017). "Our findings that PKA is an effector of EPO/JAK2 signaling implicate PKA activity not only in the pathogenesis of EPP but also a spectrum of hematologic diseases." (PMID 28553927, 2017). "These rare BCR-JAK2 fusions suggest common pathways between JAK2 activation and the natural history of lympho/myeloproliferative hematologic malignancies." (PMID 25789185, 2015). "It exhibits potent efficacy in vitro and in several in vivo models of Jak2-mediated hematological disease." (PMID 25162558, 2014). "JAK2 plays essential roles in transmitting signals from multiple cytokine receptors, and has emerged as a prominent drug target in hematological malignancies." (PMID 23592968, 2013). "TEL fusion proteins with other tyrosine kinases, such as ABL1, ABL2, JAK2, NTRK3, FFGR3, and PDGFRB, have also been associated with various hematologic malignancies, though direct comparisons between these fusion proteins in mouse models is not complete." (PMID 24116232, 2013).